ENSG00000308388 (novel transcript)
Gene: Long non-coding RNA gene on chromosome 19 (40,114,401 to 40,169,695, reverse strand). Ensembl gene ENSG00000308388.
Gene Ontology:
Biological process: RNA processing
Cellular component: nucleolus